PPP2R2D (protein phosphatase 2 regulatory subunit Bdelta)
Description:
Substrate-recognition subunit of protein phosphatase 2A (PP2A) that plays a key role in cell cycle by controlling mitosis entry and exit. Involved in chromosome clustering during late mitosis by mediating dephosphorylation of MKI67 (By similarity). The activity of PP2A complexes containing PPP2R2D (PR55-delta) fluctuate during the cell cycle: the activity is high in interphase and low in mitosis (By similarity).
Synonyms: MDS026; B55delta; B55D
Tractability: PROTAC: ubiquitination databases record sites on it; its protein half-life has been measured.
Gene: Protein-coding gene on chromosome 10 (131,900,977 to 131,959,834, forward strand). Ensembl gene ENSG00000175470.
Subcellular location: Cytoplasm
Subcellular location (Human Protein Atlas): Cytosol
Pathways (Reactome):
Cell Cycle: MASTL Facilitates Mitotic Progression
Gene Ontology:
Molecular function: protein binding; enzyme-substrate adaptor activity; protein phosphatase regulator activity
Biological process: exit from mitosis; mitotic cell cycle; regulation of chromosome segregation
Cellular component: cytoplasm; cytosol; protein phosphatase type 2A complex
Genetic constraint (gnomAD): Loss-of-function variants: 7 observed, 21.73 expected, observed/expected ratio (o/e) 0.32, 90% interval 0.18 to 0.61. The upper end of that interval is the gene's LOEUF score, 0.61, which puts it in group 2 of 6, group 1 being the genes least tolerant of losing a copy. Missense variants: 279 observed, 349.82 expected, observed/expected ratio (o/e) 0.8, 90% interval 0.72 to 0.88. Synonymous variants: 123 observed, 134.39 expected, observed/expected ratio (o/e) 0.92, 90% interval 0.79 to 1.06.
Homologues: Orthologues: chimpanzee PPP2R2D (100% identical), macaque PPP2R2D (99% identical), dog PPP2R2D (97% identical), mouse Ppp2r2d (97% identical), rat Ppp2r2d (97% identical), guinea pig PPP2R2D (96% identical), tropical clawed frog ppp2r2d (95% identical), zebrafish ppp2r2d (94% identical), Caenorhabditis elegans sur-6 (67% identical). Paralogues in human: PPP2R2A (87% identical), PPP2R2B (83% identical), PPP2R2C (80% identical).
Diseases named in the same sentence as PPP2R2D in open-access papers:
PPP2R2D is named in the same sentence as 23 diseases in open-access papers, as found by Europe PMC text mining. Sharing a sentence is not in itself a finding about the gene and the disease. The quoted sentences say what the papers report.
hepatocellular carcinoma (3 papers, 2017 to 2022). A malignant tumor that arises from hepatocytes. "B55δ, encoded by the PPP2R2D gene, can increase the suppressive effect of cisplatin (cDDP) in Hepatocellular carcinoma (HC), miR-133b was up-regulated in HC cells and directly target PPP2R2D and suppress its expression and further disrupt its effect in improving chemotherapeutic sensitivity." (PMID 28422730, 2017).
Obesity (3 papers, 2018 to 2026). Accumulation of substantial excess body fat. "A cross-sectional study that aimed to identify the DNA methylation signatures at genes modulating dopamine signaling that are associated with obesity features found that PPP2R2D is hypermethylated in the blood of adults with abdominal obesity." (PMID 31639064, 2019).
developmental delay (2 papers, 2014 to 2015). "According to an in silico evaluation, we have suggested that PPP2R2D and BNIP3 losses are likely a cause of developmental delay in the index patient." (PMID 24649379, 2014).
joint disease (2 papers, 2019 to 2021). "Changes in the methylation levels of genes associated with skin/joint disease (MBP, OSBPL5, SNORD115, and HCG26) and joint disease (IL22, ELF5, PPP2R2D, PTPRN2, and HCG26) were found." (PMID 33869291, 2021). "Biological inference prioritized notable DMRs associated with skin disease (SIGLEC14, JAM3, PCOLCE, RXRB), skin and/or joint disease (MBP, OSBPL5, SNORD115, HCG26), and joint disease (IL22, ELF5, PPP2R2D, PTPRN2, HCG26)." (PMID 30779748, 2019). "Although few DMRs exceeded a 10% change in methylation, it is noteworthy that many of those which did play roles in the pathogenesis of skin disease (SIGLEC14, JAM3, PCOLCE, RXRB, ELF5, IL22), joint disease (MBP, HCG26, IL22, PPP2R2D, PTPRN2) or are known to be imprinted (OSBPL5, SNORD115)." (PMID 30779748, 2019).
alcoholic liver diseases (1 paper, 2022). A disorder caused by damage to the liver parenchyma due to alcohol consumption. "Altogether, these findings strengthen the functional role of AhR in regulating the PPP2R2D-AMPK axis and the resultant autophagy pathway in alcoholic liver disease." (PMID 36241614, 2022).
autoimmune disease (1 paper, 2020). A disorder resulting from loss of function or tissue destruction of an organ or multiple organs, arising from humoral or cellular immune responses of the individual to their own tissue constituents. "Patients with autoimmune diseases who have increased levels of PPP2R2D in T cells could benefit from proper inhibitors." (PMID 32897879, 2020). "In summary, we have shown that PPP2R2D, a regulatory subunit of PP2A, suppresses the production of IL-2 and Treg activity, and its specific targeting should increase IL-2 production and Treg activity in autoimmune diseases." (PMID 32897879, 2020).
Autoimmunity (1 paper, 2020). The occurrence of an immune reaction against the organism's own cells or tissues. "Mice with T cell–specific PPP2R2D deficiency display less systemic autoimmunity when exposed to a TLR7 stimulator." (PMID 32897879, 2020). "PPP2R2D is increased in T cells from patients with SLE, and mice lacking this subunit in T cells develop less autoimmunity." (PMID 32897879, 2020).
epilepsy (1 paper, 2017). A brain disorder characterized by episodes of abnormally increased neuronal discharge resulting in transient episodes of sensory or motor neurological dysfunction, or psychic dysfunction. "All genes except for IL20RB, PPP2R2D and MZB1 were more expressed in the RNCC group as compared to the Idiopathic Epilepsy group." (PMID 28622332, 2017).
lupus- (1 paper, 2020). "At the translational level, we show that PPP2R2D deficiency in T cells alleviates imiquimod-induced lupus-like pathology." (PMID 32897879, 2020). "In fact, we present evidence that PPP2R2D deficiency in T cells alleviates imiquimod-induced lupus-like pathology in mice." (PMID 32897879, 2020). "PPP2R2D deficiency in T cells alleviates imiquimod-induced lupus-like pathology in mice." (PMID 32897879, 2020). "We show that the regulatory subunit PPP2R2D is increased in T cells from people with systemic lupus erythematosus and regulates IL-2 production." (PMID 32897879, 2020).
melanoma (1 paper, 2020). A malignant, usually aggressive tumor composed of atypical, neoplastic melanocytes. "Our findings are in conceptual agreement with a recent report demonstrating that T cells with silenced PPP2R2D produced more IL-2 and other cytokines when transferred into mice along with melanoma cells." (PMID 32897879, 2020).
steatosis (1 paper, 2022). Increased lipid within the cytoplasm of cells. "Furthermore, AhR, CYP1A1, and PPP2R2D expression in ALD patients increased with decreases in p-AMPKα as histological steatosis scores worsened." (PMID 36241614, 2022).
tumor (10 papers, 2015 to 2025). "The levels of PPP2R2A, PPP2R2B, and PPP2R2D genes expression in tumor tissues of HCC patients from the GEO (GSE76427) and TCGA-LIHC dataset were lower than those in peritumor tissues." (PMID 37554285, 2023). "This discovery aligns with previous knowledge demonstrating that while PP2A acts primarily as a tumour suppressor, certain subunits, including Ppp2r2d, show the ability to positively regulate signalling pathways such as the MAPK signalling cascade." (PMID 35621492, 2022). "SAT1 modulates cell migration and resistance in multiple tumor types, whereas PPP2R2D is a component of the tumor-suppressive phosphatase PP2A." (PMID 32029502, 2020). "For instance, Ppp2r2d was identified in the in vivo screen that, when knocked down with shRNA, reduced tumor size." (PMID 28101055, 2016). "The difference in PPP2R2D expression between normal and tumor cells suggested it as a potential biomarker for HCC." (PMID 27074866, 2016). "PPP2R2D acts as a tumor suppressor in the signaling pathway in BC." (PMID 33910530, 2021). "As the in vivo experiments include additional cellular components than included in the mathematical models, the results suggest that altering Ppp2r2d may influence the control of tumor growth through an indirect mechanism." (PMID 28101055, 2016). "Indeed, knockdown of Ppp2r2d allowed greater T cell proliferation in the presence of antigen at the tumour site, and improved survival despite microenvironment inhibition and a lack of co-stimulatory support." (PMID 26861383, 2016). "T cells with shRNA knockdown of Ppp2r2d, Eif2ak3 and Smad2 were highly enriched, suggesting these genes—or their downstream pathways—may contribute towards T cell dysfunction in the tumour setting." (PMID 26861383, 2016). "The selective transcriptional downregulation of ubiquitin ligase adaptors and PP2A phosphatase regulatory isoforms PPP2R2C and PPP2R2D in GBM versus AS, ODG, and non-tumor brain samples suggested an intricate role of the ubiquitination machinery on Hippo signaling." (PMID 35896929, 2023). "In contrast, PPP2R2D showed an increased proportion of the 3′-UTR long form in PDAC cell lines and patient samples as compared to the short form, suggesting greater use of the distal PAS for this putative tumor-suppressive gene." (PMID 32029502, 2020). "Taken together, the expression of PPP2R2D was down-regulated in HCC tissues and cells, indicating that PPP2R2D might act as a tumor suppressor in the chemotherapy of HCC." (PMID 27074866, 2016). "In two different HCC cohorts (Accession No.: GSE59259 and GSE6764), the tumor tissues exhibited relatively low PPP2R2D expression levels." (PMID 27074866, 2016). "For example, transducing tumor-specific CD8+ T cells with pooled lentiviral shRNA libraries before adoptive transfer into tumor-bearing mice determined that protein phosphatase 2, regulatory B subunit (Ppp2r2d) is a novel target in TIL to enhance immune function." (PMID 26393659, 2015).
cancer (2 papers, 2016 to 2020). A tumor composed of atypical neoplastic, often pleomorphic cells that invade other tissues. "In contrast, PPP2R2A was the most deleted gene found in > 20% of samples across 17 cancers, followed by the deletion of SLC2A4 in 16 cancers and five additional genes (FOXO3, PPP2CB, PPP2R2D, PPP2R5C and PPP2R5E) in 15 cancer types." (PMID 32807122, 2020).
neurodegenerative disease (1 paper, 2025). A disorder of the central nervous system characterized by gradual and progressive loss of neural tissue and neurologic function. "The four folds upregulation of ubiquitin C-terminal hydrolase L1 (UCHL1) and PPP2R2D, a subunit of protein phosphatase 2A, suggests altered signalling pathways and protein turnover in human brain, which are associated with neurodegenerative diseases." (PMID 40520681, 2025).
PPP2R2D also shares sentences with these, for which no sentence is quoted: Intellectual disability (2 papers); Abdominal obesity (1); asthma (1); atherosclerosis (1); diabetes (1); diffuse idiopathic skeletal hyperostosis (1); Hypertension (1); neurodevelopmental disorder (1); type 2 diabetes (1).